GARIN3 (golgi associated RAB2 interactor family member 3)
Description:
May be involved in RNA biogenesis.
Synonyms: FAM71B; MGC26988; GARI-L3
Tractability: No criterion of Open Targets' tractability assessment is met for any kind of drug.
Gene: Protein-coding gene on chromosome 5 (157,161,846 to 157,166,264, reverse strand). Ensembl gene ENSG00000170613.
Subcellular location: Golgi apparatus; Nucleus, Cajal body
Gene Ontology:
Cellular component: nucleus; Golgi apparatus; Cajal body; sperm head
Genetic constraint (gnomAD): Loss-of-function variants: 14 observed, 17.54 expected, observed/expected ratio (o/e) 0.8, 90% interval 0.53 to 1.25. The upper end of that interval is the gene's LOEUF score, 1.25, which puts it in group 5 of 6, group 1 being the genes least tolerant of losing a copy. Missense variants: 778 observed, 805.36 expected, observed/expected ratio (o/e) 0.97, 90% interval 0.91 to 1.02. Synonymous variants: 266 observed, 299.33 expected, observed/expected ratio (o/e) 0.89, 90% interval 0.8 to 0.98.
Homologues: Orthologues: chimpanzee GARIN3 (94% identical), macaque GARIN3 (90% identical), dog GARIN3 (66% identical), rabbit GARIN3 (66% identical), pig GARIN3 (65% identical), rat Garin3 (57% identical), guinea pig GARIN3 (57% identical), mouse Garin3 (56% identical). Paralogues in human: GARIN4 (48% identical), GARIN5B (23% identical), GARIN6 (21% identical), GARIN2 (17% identical), GARIN1B (13% identical), GARIN1A (11% identical), GARIN5A (10% identical).
Diseases named in the same sentence as GARIN3 in open-access papers:
GARIN3 is named in the same sentence as 4 diseases in open-access papers, as found by Europe PMC text mining. Sharing a sentence is not in itself a finding about the gene and the disease. The quoted sentences say what the papers report.
infertile (2 papers, 2023 to 2024). "In particular, Garin3 KO mice showed lower PC2 value with less variation, which may be related to severe ZP penetration failure and infertility." (PMID 38935810, 2024).
GARIN3 also shares sentences with these, for which no sentence is quoted: frontotemporal dementia (1 paper); prostate carcinoma (1); tumor (1).